TEX12 (testis expressed 12)
Description:
Component of the transverse central element of synaptonemal complexes (SCS), formed between homologous chromosomes during meiotic prophase (By similarity). Requires SYCP1 in order to be incorporated into the central element (By similarity).
Tractability: No criterion of Open Targets' tractability assessment is met for any kind of drug.
Gene: Protein-coding gene on chromosome 11 (112,167,372 to 112,172,556, forward strand). Ensembl gene ENSG00000150783.
Subcellular location: Chromosome
Subcellular location (Human Protein Atlas): Basal body; Centrosome
Pathways (Reactome):
Reproduction: Meiotic synapsis
Gene Ontology:
Molecular function: protein binding
Biological process: homologous chromosome pairing at meiosis; homologous recombination; reciprocal meiotic recombination; synaptonemal complex assembly
Cellular component: centrosome; ciliary basal body; central element; chromosome; condensed nuclear chromosome; synaptonemal complex
Genetic constraint (gnomAD): Loss-of-function variants: 2 observed, 2.58 expected, observed/expected ratio (o/e) 0.78, 90% interval 0.3 to 1.81. That is too few expected variants to judge how well the gene tolerates losing a copy. Missense variants: 33 observed, 37.98 expected, observed/expected ratio (o/e) 0.87, 90% interval 0.66 to 1.16. Synonymous variants: 18 observed, 17.33 expected, observed/expected ratio (o/e) 1.04, 90% interval 0.72 to 1.54.
Homologues: Orthologues: macaque TEX12 (98% identical), dog TEX12 (89% identical), pig TEX12 (87% identical), mouse Tex12 (85% identical), guinea pig TEX12 (82% identical), rat Tex12 (72% identical).
Diseases named in the same sentence as TEX12 in open-access papers:
TEX12 is named in the same sentence as 9 diseases in open-access papers, as found by Europe PMC text mining. Sharing a sentence is not in itself a finding about the gene and the disease. The quoted sentences say what the papers report.
Infertility (3 papers, 2011 to 2021). "Detailed analyses of Syce2 and Tex12 knockout mice showed that loss of each of these two genes causes infertility in both sexes." (PMID 21637789, 2011).
hepatocellular carcinoma (2 papers, 2018 to 2021). A malignant tumor that arises from hepatocytes. "With the exception of TEX12, these proteins are associated with other cancers, such as hepatocellular carcinoma, breast cancer, and prostate cancer." (PMID 29713252, 2018). "To validate our inference that TEX12 expression could contribute to cancer, we examined the biology of TEX12 in tumourigenesis using mouse models of lymphoma and hepatocellular carcinoma." (PMID 34880391, 2021).
prostate carcinoma (2 papers, 2018 to 2021). A carcinoma that arises from epithelial cells of the prostate gland. "Reciprocally, silencing the ten eleven translocation (TET1-3) demethylating enzymes for 72 h in TEX12-positive PC3 prostate cancer cells was not sufficient to suppress TEX12 expression." (PMID 34880391, 2021).
Azoospermia (1 paper, 2018). Absence of any measurable level of sperm,whereby spermatozoa cannot be observed even after centrifugation of the semen pellet. "Therefore, this study aimed to replicate this finding in humans byexamining the expression levels of TEX11, TEX12,TEX14, and TEX15 in the testis tissue of patients withnon-obstructive azoospermia and comparing them against controls." (PMID 29932616, 2018).
lymphoma (1 paper, 2021). A malignant (clonal) proliferation of B- lymphocytes or T- lymphocytes which involves the lymph nodes, bone marrow and/or extranodal sites. "Mining of public mass-spectrometry datasets identified TEX12 peptides containing Y48 in the phosphorylated form from human lymphoma cell lines (Phosphosite), suggesting that this might be a functional phosphorylation site." (PMID 34880391, 2021).
cancer (4 papers, 2018 to 2022). A tumor composed of atypical neoplastic, often pleomorphic cells that invade other tissues. "In this manuscript we demonstrate that aberrant expression of TEX12 is common in cancer where it is associated with centrosome amplification and poor prognosis." (PMID 34880391, 2021). "In somatic cells, ectopically expressed TEX12 similarly localises to centrosomes, where it is associated with centrosome amplification, a pathology correlated with cancer development." (PMID 34880391, 2021). "Moreover, our findings may facilitate in vivo discoveries, such as by establishing imaging methods that differentiate TEX12 dimers and SYCE2-TEX12 complexes, and in developing new diagnostic, prognostic and therapeutic methods for TEX12-positive cancers." (PMID 36071143, 2022). "The cancer-testis antigen TEX12 is a coiled-coil protein that functions in chromosome synapsis and centrosome structure in meiosis, and can lead to centrosome dysfunction in cancers 8,9." (PMID 36071143, 2022). "Our findings provide the structural basis for SYCE2-independent roles of TEX12, including the possible regulation of SC assembly, and its known functions in meiotic centrosomes and cancer." (PMID 36071143, 2022). "Aberrant expression of TEX12 in somatic cells contributes to increased proliferation and centrosomal aberrations, both common features of cancer." (PMID 34880391, 2021). "Immunofluorescent staining, performed in a number of cancer cell lines and upon ectopic expression in mitotic cells, consistently revealed expression of TEX12 in dot-like peri-nuclear foci." (PMID 34880391, 2021). "Here we report that meiotic synaptonemal complex protein TEX12 is frequently mis-expressed in cancer." (PMID 34880391, 2021). "We further confirmed that this proliferative defect was not simply due to cell death but due to a G2/M cell cycle arrest, establishing that TEX12 is required for cell proliferation in a subset of human cancers." (PMID 34880391, 2021). "Our experimental and bioinformatic analysis suggests that TEX12 is a potential driver of cancer progression." (PMID 34880391, 2021). "Thus, our elucidation of TEX12 structure and its regulation by the C-terminal tip provide the molecular basis for ongoing functional studies of TEX12’s biological roles in the SC, centrosomes and cancer." (PMID 36071143, 2022). "Thus, to understand TEX12’s centrosome function in meiosis and cancer, alongside other potential SYCE2-independent cellular roles, we sought to elucidate the structure of the TEX12 dimer." (PMID 36071143, 2022). "Moreover, somatic expression of TEX12 is aberrantly activated via retinoic acid signalling, which is commonly disregulated in cancer." (PMID 34880391, 2021). "Thus, the Y48 phosphorylation site is important for the centrosomal pathology in TEX12 positive cancer cells." (PMID 34880391, 2021). "We conclude that TEX12 normally localises to meiotic centrosomes, but its misexpression in somatic cells can contribute to pathological amplification and dysfunction of centrosomes in cancers." (PMID 34880391, 2021). "Indeed, TEX12 is identified as a cancer-testis antigen and proliferation of some cancer cells is TEX12-dependent." (PMID 34880391, 2021). "To test whether TEX12 is important for cancer cell growth, we performed siRNA knockdown of TEX12 in multiple cancer cell lines." (PMID 34880391, 2021). "Furthermore, induction of TEX12 re-expression following retinoic acid stimulation is of therapeutic relevance as retinoid treatment is used in oncology to force cancer cell differentiation, thereby reducing their stemness." (PMID 34880391, 2021). "The localisation of TEX12 to centrosomes in cancer cells raises the possibility that its physiological function during meiosis might also include a role at microtubule organising centres (MTOCs) in addition to its well-established role in chromosome synapsis." (PMID 34880391, 2021).
cancer (continued). "We therefore set out to investigate if, in keeping with the mechanisms of other meiosis-specific genes in cancer, the centrosomal role of TEX12 in cancer cells may represent a pseudo-meiotic function." (PMID 34880391, 2021). "In assessing how TEX12 expression might lead to poor prognosis in human cancers, we found that TEX12 expression and gene amplification each predict more aggressive disease." (PMID 34880391, 2021). "Furthermore, we found TEX12 to be a GCCG that is widely expressed in ∼15% of cancer patients." (PMID 34709374, 2021). "Thus, given our finding that TEX12 localises to centrosomes, we wondered whether aberrant expression of TEX12 in cancer cells might promote centrosome amplification." (PMID 34880391, 2021). "Notably, we observed that TEX12 expression induced a pattern of enlarged and diffuse centrosomal staining indicative of rosette centrosomes/amplified centrosomes, which have been described as a common feature of cancer cells." (PMID 34880391, 2021). "In contrast, TEX12-negative PEO1 cancer cells and non-transformed fibroblasts were not affected by TEX12 silencing, ruling out off-target effects of siRNA treatment." (PMID 34880391, 2021). "Here, we report a localisation for TEX12, independent of the SC, within centrosomes of meiotic and cancer cells." (PMID 34880391, 2021). "However as TEX12 is not the sole driver of centrosome amplification, silencing its expression in cancer cells characterised by amplified centrosomes was not sufficient to restore normal centrosome numbers even though a non-significant decreasing trend can be observed." (PMID 34880391, 2021).
tumor (2 papers, 2021). "We analysed large-scale transcriptomic datasets of patient samples and observed that a synaptonemal complex protein, TEX12, was aberrantly expressed in a wide variety of tumours in ~10% of patients (ranging between 5 and 17%)." (PMID 34880391, 2021). "Detection at the 5 week-stage indicates that TEX12 is expressed at the very early stages of oncogenesis, prior to the formation of an overt HCC tumour in mice." (PMID 34880391, 2021).
TEX12 also shares sentences with these, for which no sentence is quoted: breast carcinoma (1 paper); osteosarcoma (1).